PIWIL3 (piwi like RNA-mediated gene silencing 3)
Description:
May play a role during spermatogenesis by repressing transposable elements and preventing their mobilization, which is essential for the germline integrity. Acts via the piRNA metabolic process, which mediates the repression of transposable elements during meiosis by forming complexes composed of piRNAs and Piwi proteins and govern the methylation and subsequent repression of transposons. Directly binds piRNAs, a class of 24 to 30 nucleotide RNAs that are generated by a Dicer-independent mechanism and are primarily derived from transposons and other repeated sequence elements. Besides their function in transposable elements repression, piRNAs are probably involved in other processes during meiosis such as translation regulation (By similarity).
Synonyms: HIWI3
Tractability: No criterion of Open Targets' tractability assessment is met for any kind of drug.
Gene: Protein-coding gene on chromosome 22 (24,719,034 to 24,774,720, reverse strand). Ensembl gene ENSG00000184571.
Subcellular location: Cytoplasm
Subcellular location (Human Protein Atlas): Cytoplasmic bodies
Gene Ontology:
Molecular function: piRNA binding; nucleic acid binding; RNA binding
Biological process: piRNA processing; spermatogenesis
Cellular component: cytoplasm; nucleus; P granule
Genetic constraint (gnomAD): Loss-of-function variants: 102 observed, 107.89 expected, observed/expected ratio (o/e) 0.95, 90% interval 0.8 to 1.11. The upper end of that interval is the gene's LOEUF score, 1.11, which puts it in group 4 of 6, group 1 being the genes least tolerant of losing a copy. Missense variants: 1,018 observed, 1,105.9 expected, observed/expected ratio (o/e) 0.92, 90% interval 0.87 to 0.97. Synonymous variants: 369 observed, 392.6 expected, observed/expected ratio (o/e) 0.94, 90% interval 0.86 to 1.02.
Homologues: Orthologues: chimpanzee PIWIL3 (99% identical), macaque PIWIL3 (95% identical), rabbit PIWIL3 (54% identical), pig PIWIL3 (53% identical), tropical clawed frog piwil3 (46% identical), zebrafish piwil1 (45% identical), tropical clawed frog piwil3 (45% identical), Drosophila melanogaster aub (31% identical), Drosophila melanogaster piwi (31% identical), Caenorhabditis elegans prg-1 (29% identical). Paralogues in human: PIWIL1 (50% identical), PIWIL4 (40% identical), PIWIL2 (33% identical).